ZFP36 (ZFP36 zinc finger CCCH-type)
Diseases named in the same sentence as ZFP36 in open-access papers (continued):
Sharing a sentence is not in itself a finding about the gene and the disease.
prostate carcinoma (8 papers, 2008 to 2025). A carcinoma that arises from epithelial cells of the prostate gland. "Loss of ZFP36/TTP in prostate cancer patients selects for aggressive disease." (PMID 39560993, 2024). "In prostate cancer, EGR3 suppresses metastasis by inducing the expression of tumor suppressor genes, such as ZFP36 and SOCS3, while additional evidence suggests that EGR3 loss correlates with relapse and reduced survival." (PMID 40649712, 2025). "That study demonstrated its ability to activate specific genes—ZFP36, GADD45B, and SOCS3—in a prostate cancer cell line." (PMID 38543002, 2024). "A newly predicted interaction between NEDD9 and ZFP36 in particular was validated by co-immunoprecipitation, as was NEDD9's potential biological role in prostate cancer cell growth regulation." (PMID 27078000, 2016). "Our predicted NFκB pathway suggested 8 novel genes which were found to be highly down-regulated in lethal prostate cancer and highly functionally related to NFκB, namely ATF3, CXCL2, DUSP5, JUNB, NEDD9, SELE, TRIB1, and ZFP36." (PMID 27078000, 2016). "Notable genes in the predicted pathway included ATF3, JUNB, KLF6, NR4A2, ZFP36, DUSP5 and NEDD9, as well as STAT3 and IRF1 as novel upstream regulators, and SELE, CXCL1 and CXCL2 as novel downstream targets of NFκB in prostate cancer." (PMID 27078000, 2016). "This is complementary with our predictions, suggesting that after being regulated by KLF6, ZFP36 directly binds to NEDD9, thus acting as another novel upstream inhibitor of NFκB with a role in the amelioration of prostate cancer." (PMID 27078000, 2016). "A 5-gene recurrence predictor of prostate cancer contains KLF6, three common ARACNe-based predictions between MYC and KLF6 (FOS, JUNB and ZFP36), and PPFIA3, which is functionally related to another predicted target of KLF6 (PPFIBP2)." (PMID 18190704, 2008). "All of these genes were down-regulated in patients who had disease that relapsed after a prostatectomy, which could be the result of negative feedback loops in lethal prostate cancer that turn off important cancer regulators, such as ZFP36, DUSP5, and ATF3." (PMID 27078000, 2016).
rheumatoid arthritis (8 papers, 2017 to 2024). A chronic, systemic autoimmune disorder characterized by inflammation in the synovial membranes and articular surfaces. "ZFP36 has been linked to a variety of autoimmune diseases such as rheumatoid arthritis, psoriasis, multiple sclerosis, and juvenile idiopathic arthritis." (PMID 37180137, 2023). "Overall, the arthritis in both the whole-body Zfp36-KO mice and the M-triple KO mice is similar to the pathology observed in human rheumatoid arthritis and in mouse models of rheumatoid arthritis, such as collagen antibody-induced arthritis." (PMID 37903626, 2024). "These mechanistic profiles of ZFP36 raise the possibility that the induction of ZFP36 expression could be an effective therapeutic strategy against inflammatory diseases, particularly in rheumatoid arthritis and other autoimmune diseases in which TNF-α secretion is increased." (PMID 32655569, 2020).
autoimmune disease (7 papers, 2019 to 2025). A disorder resulting from loss of function or tissue destruction of an organ or multiple organs, arising from humoral or cellular immune responses of the individual to their own tissue constituents. "Zinc finger protein 36 (ZFP36) participates in posttranscriptional regulation by targeting different mRNAs, which was closely related to inflammatory diseases and autoimmune disease." (PMID 36923221, 2023). "Here we show that TTP/Zfp36 expression is indispensable for controlling TNFα levels in mammary cells, even in the absence of infection, mutations, or autoimmune diseases." (PMID 38274271, 2023). "This suggestion is consistent with the observation that mice with prolonged ZFP36 expression, resulting from removal of the autoinhibitory sequence in the Zfp36 3′UTR, show much reduced disease severity in an experimental autoimmune encephalitis, a T cell‐driven autoimmune disease." (PMID 41211771, 2025).
Arthritis (5 papers, 2017 to 2024). Inflammation of a joint. "The failure of weight gain, arthritis, and early death could be prevented completely by two normal alleles of any of the three paralogues, and even one normal allele of Zfp36 or Zfp36l2 was enough to prevent the inflammatory phenotype." (PMID 37903626, 2024). "We found that simultaneous deficiency of Zfp36, Zfp36l1, and Zfp36l2 in myeloid cells led to the spontaneous development of an early lethal phenotype, with severe arthritis, myeloid hyperplasia, bone resorption, and increased levels of cytokines and chemokines." (PMID 37903626, 2024). "Zfp36-KO mice develop a severe inflammatory phenotype characterized by myeloid hyperplasia, arthritis, failure of weight gain, and autoimmunity." (PMID 37903626, 2024). "All Zfp36+/+ mice developed arthritis after injection of arthritogenic K/BxN serum, with transient weight loss and swelling of ankles and footpads." (PMID 27597652, 2017).
asthma (5 papers, 2020 to 2025). "It has been described that the expression of members of the TTP family (ZFP36, ZFP36 L2) was reduced in T cell samples of asthma patients compared to T cells obtained from healthy donors." (PMID 40095032, 2025). "Interestingly, ZFP36 was identified as a specific and shared biological biomarker in COPD, asthma, and IPF, and was verified as a risk-predicting factor in our study." (PMID 34671612, 2021). "They include RBM42, STX5, and TRIM41 in asthma, CYP27A1, GM2A, LGALS9, SPI1, and NLRC4 in COPD, as well as ATF3, PPP1R15A, ZFP36, SOCS3, NAMPT, and GADD45B in IPF." (PMID 31952466, 2020). "These genes included RBM42, STX5, and TRIM41 in asthma, CYP27A1, GM2A, LGALS9, SPI1, and NLRC4 in COPD, ATF3, PPP1R15A, ZFP36, SOCS3, NAMPT, and GADD45B in IPF, LRRC48 and CETN2 in asthma-COPD, COL15A1, GIMAP6, and JAM2 in asthma-IPF and LMO7, TSPAN13, LAMA3, and ANXA3 in COPD-IPF." (PMID 31952466, 2020).
cervical cancer (5 papers, 2009 to 2024). A primary or metastatic malignant neoplasm involving the cervix. "Our work extends the knowledge about mechanisms involved in cervical cancer inhibition and ZFP36 regulation by metformin." (PMID 39026155, 2024). "Since HeLa is a well-characterized HPV+ cervical cancer cell line, it could be possible that the activated expression of the immune response genes by ZFP36 overexpression is due to an attempt to reactivate the expression of the HPV genome." (PMID 31046669, 2019). "The TTP gene (ZFP36)is located on 19q13.1 and does not appear tobe a target of genomic loss or rearrangement in cervical cancer." (PMID 20157568, 2009).
colorectal cancer (5 papers, 2016 to 2025). A primary or metastatic malignant neoplasm that affects the colon or rectum. "This is the case for Early growth Response 1 (EGR1), a major transcription factor involved in ZFP36 transcription, which is downregulated in several cancers, including colorectal cancer or HCC." (PMID 39941720, 2025). "To this regard, we observed in a previous work that ZFP36 expression in colorectal carcinoma cell lines is inversely correlated to Wnt/CTNNB1 pathway activity." (PMID 32784485, 2020).
COVID-19 (5 papers, 2021 to 2023). A disease caused by infection with severe acute respiratory syndrome coronavirus 2. "Studies on COVID-19 showed that ZFP36 inhibited T cell activation, and proliferation during viral infection and the expression level of ZFP36 changed dramatically during infection." (PMID 36437952, 2022). "Neutrophil transcripts which are robustly expressed in the uninfected state, including anti-proliferation and pro-apoptotic genes (LST1, G0S2, CPPED1, BTG2, PMAIP1) and anti-inflammatory genes (AMPD2, SEC14L1, ZFP36), are significantly downregulated in COVID-19 patients." (PMID 36466858, 2022).
dermatitis (5 papers, 2020 to 2024). An inflammatory process affecting the skin. "Previous studies have found that ZFP36 has an important role in the control of local skin inflammation by targeting cytokine genes, and loss of ZFP36 in epidermal cells contributes to inflammatory phenotype in skin conditions such as psoriasis." (PMID 38388834, 2024).
lung carcinoma (5 papers, 2021 to 2025). "Loss of ZFP36 can promote proliferation, migration, and invasion of nonsmall cell lung cancer cells." (PMID 39495117, 2024). "This suggests that the functional role and clinical relevance of ZFP36 in lung cancer remain largely unexplored and warrant further investigation." (PMID 40361912, 2025). "In lung cancer, the five most important mRNAs were HBB, HBA2, MT2A, ZFP36, and DUSP1." (PMID 39495117, 2024).
Obesity (5 papers, 2018 to 2026). Accumulation of substantial excess body fat. "They elucidated that ZFP36 deficiency-driven obesity manifested through white adipose tissue adipocyte hypertrophy, mediated by the reduced expression of lipid metabolism regulators PLIN1, ATGL, and HSL." (PMID 40732992, 2025). "Evidence from human genetics identifies ZFP36 as a promising candidate gene for obesity-related metabolic complications." (PMID 41596407, 2026). "Their findings establish adipose ZFP36 as a critical modulator of diet-induced obesity in the ZFP36/RNF128/Sirt1 signaling axis." (PMID 40732992, 2025). "ZFP467 can regulate the differentiation of adipose-derived stem cells; ZFP36 was identified as a candidate gene for obesity-related metabolic complications." (PMID 31316554, 2019). "Then we validated 7 obesity or lipid metabolism related genes (Hif1a, Spon1, H19, Adrb2, Vldlr, Zfp36, Smad3), and found that compared to CTL group, Vldlr was hypermethylated and low expressed, and Hif1α was demethylated and high expressed in the VDD group." (PMID 29321608, 2018). "Future studies should focus on further elucidating the downstream effects of dysregulated lipolysis in the context of obesity-related pathologies, as well as exploring potential therapeutic interventions targeting the ZFP36/RNF128/Sirt1 pathway to mitigate metabolic dysfunction." (PMID 41596407, 2026). "Furthermore, the upstream regulation of ZFP36 remains an open question: what signals, such as hormones from other organs or nutrients, control its expression and activity, and why is it downregulated in obesity?" (PMID 41596407, 2026). "Future studies could explore the efficacy of gene therapy or small-molecule agonists designed to upregulate or mimic ZFP36 activity in adipose tissue, testing whether such interventions can reverse or prevent obesity and insulin resistance in preclinical models." (PMID 41596407, 2026). "Overall, adipose ZFP36 emerges as a protective post-transcriptional regulator that limits adipocyte expansion and insulin resistance through the RNF128–Sirt1 axis, and its downregulation in obesity contributes to worsening metabolic outcomes." (PMID 41596407, 2026).
atherosclerosis (4 papers, 2019 to 2025). A disease characterized by the build-up of fatty material and calcium deposition in the arterial wall resulting in partial or complete occlusion of the arterial lumen. "ZFP36 also represses the transcriptional activation of NF-kB by reducing its nuclear import, suggesting that ZFP36 is a potential target for preventing atherosclerosis." (PMID 36552825, 2022). "ZFP36 and PTGDS have anti-inflammatory properties, which reduce vascular inflammation and prevent atherosclerosis." (PMID 37491214, 2023). "Though CTA-384D8.35, CTB-114C7.4 and miR-4497 have not been studied yet, their functions could be interpreted by their target genes in the ceRNA network, including inflammatory responses (CCL3, ZFP36, IER3), apoptosis (EGR1), atherosclerosis and myocardial ischemia (FOS)." (PMID 31443660, 2019).
colon carcinoma (4 papers, 2015 to 2023). "ZFP36, ZFP36L1 and ZFP36L2 mRNA levels were generally increased in the colon cancer cells by high concentration of LPS treatment." (PMID 37705049, 2023). "SYBR Green qPCR showed that TTP/ZFP36 and ZFP36L1 were expressed in similar levels but ZFP36L2 mRNA was barely detectable in the colon cancer cells." (PMID 33723275, 2021). "According to gene expression profiles, in the 80 samples considered – composed of 23 normal colon mucosa (Normal), 30 primary colon carcinoma (CRC) and 27 liver metastases (Mts) – the expression of ZFP36 gene is significantly decreased when comparing primary tumour with normal counterpart." (PMID 27463018, 2016). "However, treatment of our cell models with the DNMT inhibitor 5-Aza-dC did not induce TTP expression, suggesting that this mode of epigenetic repression does not appear to play a role in ZFP36 silencing in colon cancer." (PMID 26343742, 2015). "HDAC inhibitors may affect the expression/activity of other transcription factors known to regulate ZFP36 transcription such as Smad3, Smad4, AP1, c-myc or NFκB but also some microRNAs, such as miR-29a, which downregulates TTP in a breast cancer model and is known to be upregulated in colon cancer." (PMID 26343742, 2015).
melanoma (4 papers, 2017 to 2023). A malignant, usually aggressive tumor composed of atypical, neoplastic melanocytes. "Another high-ranked gene, ZFP36 (2nd) inhibits proliferation of A375 melanoma cell lines when maintained at high levels." (PMID 29017547, 2017). "Therefore, we asked whether ZFP36 is necessary for NOXA mRNA decay upon BRAF inhibition in melanoma cells." (PMID 31727958, 2019).
Sepsis (4 papers, 2014 to 2023). Sepsis is defined as life-threatening organ dysfunction caused by a dysregulated host response to infection. "This is particularly notable, as mice with myeloid deficiency of ZFP36 show extreme susceptibility to sepsis induced by LPS." (PMID 25299049, 2014). "Meanwhile, up-regulating the expression of Zfp36 gene can suppress the inflammatory response and induce the autophagy to clear bacteria in sepsis model mice, thereby improving sepsis outcomes." (PMID 35923893, 2022). "We also used a mouse model of sepsis-induced liver failure, and confirmed through qRT-PCR detection that ferroptosis-related genes Hmox1, Slc3a2, Jun and Zfp36 were significantly correlated with sepsis-induced liver failure." (PMID 35923893, 2022). "Therefore, we screened the ferroptosis-related genes (Hmox1, Epas1, Sirt1, Slc3a2, Jun, Plin2 and Zfp36) in this study through bioinformatics analysis, and found that these genes were highly expressed in sepsis-induced liver failure model." (PMID 35923893, 2022). "In addition, we constructed a mouse model, and confirmed through H & E staining, TUNEL staining and qRT-PCR that Hmox1, Slc3a2, Jun and Zfp36 were significantly related to sepsis-induced liver failure." (PMID 35923893, 2022). "As a result, Hmox1, Slc3a2, Jun and Zfp36 may become new therapeutic targets for sepsis-induced liver failure in the future." (PMID 35923893, 2022). "In general, the conclusions drawn from these reports are consistent with the results in our research, that is, Hmox1, Epas1, Sirt1, Slc3a2, Jun, Plin2 and Zfp36 collectively promote the development of sepsis-induced liver failure by interacting with B cells and NK cells." (PMID 35923893, 2022). "Our research also proved that Zfp36 is closely related to sepsis-induced liver failure." (PMID 35923893, 2022). "The identification of ferroptosis-related genes Hmox1, Slc3a2, Jun and Zfp36 in the present study contribute to our understanding of the molecular mechanism of sepsis-induced liver failure, and provide candidate targets for the diagnosis and treatment of the disease." (PMID 35923893, 2022). "Levels of GILZ (p = 0.018), ZFP36 (p = 0.006), FKBP5 (p = 0.012) and NRF2 (p = 0.009) mRNA were reduced, whereas CSE (p = 0.012) and HIF1α (p = 0.020) were elevated in sepsis." (PMID 32477273, 2020). "The boxplot revealed 26 differentially expressed genes between the sepsis-induced ALI and control samples: Ncf2, Slc2a6, Cd44, Txnip, Slc2a1, Ubc, Hspb1, Zfp36, Arntl, Ddit4, Tnfaip3, Txnrd1, Mt1, Hmox1, Gch1, Gclc, Stat3, Egfr, Hif1a, Bach1, Socs1, Dusp1, Cdkn1a, Fth1, Steap3, and Alox12." (PMID 37081490, 2023).
endometriosis (3 papers, 2017 to 2022). The growth of functional endometrial tissue in anatomic sites outside the uterine body. "In order to examine if HuR/TTP axis contributes to the pathophysiology of endometriosis, we evaluated expression of Zfp36, Zfp36l1, Zfp36l2 and Elavl1 in eutopic and ectopic lesions obtained from syngeneic BALB/cByJ mouse model of endometriosis." (PMID 28724967, 2017).